CD9 (CD9 molecule)
Diseases named in the same sentence as CD9 in open-access papers (continued):
Sharing a sentence is not in itself a finding about the gene and the disease.
tumor (continued). "No changes to in vitro cell proliferation were observed in this study, however, impaired in vivo tumor growth was observed in Cd9−/− mice." (PMID 32224917, 2020). "The results of subcutaneously transplanted tumor model indicated that CD9 or CD81 knockdown significantly enhanced tumorigenicity of HCC in vivo." (PMID 32350244, 2020). "In agreement with previous reports, KLF4 mRNA expression was remarkably downregulated in tumor tissues, and lower expression of CD9 and CD81 mRNAs were observed in tumor tissues as compared with adjacent normal tissues." (PMID 32350244, 2020). "Proteins such as CD9, CD63, and CD81 are located on the exosome surface, and tumor-associated markers (HER2, EpCAM) are also present on tumor-associated exosomes." (PMID 32582658, 2020). "This was unexpected as CD9 is known to play a suppressive role in cancer progression and metastasis in other tumor types such as prostate, lung, gastric, and ovarian cancers." (PMID 32224917, 2020). "TSPAN12 can promote tumor cell proliferation and colony formation, and high expression of CD9 is considered to be related to lymph node metastasis." (PMID 32694936, 2020). "CD9 was enriched in fractions 0, 1, and 2 and decreased in fraction 3 in both normal and tumor tissue exosomes." (PMID 33276608, 2020). "To date, many tumor metastasis- and invasion-related studies have focused on CD9, CD81, CD82/KAI1, CD151, and TM4SF1." (PMID 30876464, 2019). "For example, one of the fish specific genes CD9, with an ancestral root dating back to 420 million years, is involved in cell adhesion, cell motility and tumour metastasis and is essential for sperm-egg fusion." (PMID 31830141, 2019). "Studies on human tumor cells reported associations between tetraspanin expression and tumor progression showing both reduced (CD82, CD9) and increased expression (CD151, Tspan8) in various cancer types." (PMID 29896201, 2018). "Taken together, these data indicate that CD9 + exosomes released by HPV-positive tumor cells promote tumor innervation in vivo." (PMID 30327461, 2018). "After 7 h, cells were stained with tumor specific markers (e.g., CD9, CD34) and tumor viability was analyzed by flow cytometry using 7AAD and Annexin V staining." (PMID 30233577, 2018). "CD9 is reported to suppress motility and to promote adherence, leading to the suppression of tumor progression." (PMID 30356731, 2018). "By using the anterior lobes of prolactinoma model rats, the localisation of CD9-positive cells was confirmed in the tumour-induced neovascularisation region." (PMID 29615783, 2018). "To trace the intracellular trafficking of EVs upon internalization by recipient cells, we engineered malignant FEMX-I and MDA tumor cells and primary MSCs to express CD9-GFP fusion protein, resulting in the production of in vivo-labeled EVs." (PMID 28129640, 2017). "In contrast, the fraction of CD9+ exosomes with survivin positivity showed a significant change at 9 weeks, generally consistent with the patient’s tumor status (p = 0.0299)." (PMID 29383115, 2017). "The tetraspanin CD9 is broadly expressed on the surface of several cell types, including many malignant tumor cells, as well as normal hematopoietic, endothelial, and epithelial cells." (PMID 29312336, 2017). "Survivin and GFAP were evaluated both independently and together as possible tumor markers on CD9+ exosomes." (PMID 29383115, 2017). "We detected tumor-released EVs from conditioned medium and serum that are consistent to exosomes in terms of size (~110 nm) and marker proteins (CD9/TSG101/AchE)." (PMID 28928431, 2017). "These experiments strongly indicate that CD9 exerts its antitumoral effects via other avenues than influencing tumor cell proliferation." (PMID 27572323, 2016). "We also detected the exosomal markers heat shock protein 70 and CD9 in the membrane vesicles, which confirmed our successful isolation of tumor-derived exosomes." (PMID 26233326, 2016).
tumor (continued). "Correlations between elevated CD9 tumor expression and all available clinical and molecular parameters for favorable tumor biology were confirmed in the 122-tumor cohort." (PMID 27572323, 2016). "Inverse correlation between CD9 expression and tumor cell invasion was shown for ovary cancer, cervical cancer and melanoma." (PMID 26573230, 2016). "The progress of the malignant potential of GIST, connected with improving CD63 expression, is very thought-provoking, especially in light of the observations of a decline in the CD9 expression when tumours are getting more aggressive." (PMID 27795705, 2016). "We detected tetraspanin proteins (CD9, CD63, CD81), Alix and tumor susceptibility gene-101 (TSG101) of exosomal markers from rotenone treated CSCs." (PMID 25682864, 2015). "Collectively, our data indicate that CD9 is implicated in BCC invasiveness and tumor growth by mechanisms that involve specific and dynamics protruding structures of BCC plasma membrane." (PMID 25762645, 2015). "CD9 (12p13.31) regulates multiple cellular functions such as cell adhesion, migration, apoptosis, and tumor cell motility, ING4 (12p13.31) is involved in cell cycle arrest, apoptosis and senescence, and BCL-G (12p13.2) plays a role in apoptosis." (PMID 26293672, 2015). "Since CD9 overexpression led to decreased CD26 expression and suppression of tumor cell invasion, we next determined the effect of CD9 overexpression on α5β1 integrin expression." (PMID 24466195, 2014). "For oral squamous cell carcinomas, the low expression of CD9 indicated the late stage of tumor development and the low survival rate." (PMID 24788635, 2014). "In mouse xenograft study, depletion of CD26 or CD9 by shRNA inhibited in vivo tumor growth, and combined depletion of CD26 and CD9 caused prominent suppression of tumor growth in vivo." (PMID 24466195, 2014). "Prior to the stage of the CD9 mediating interactions between tumor cells and ECs, matrix metalloproteinases (MMPs) are important in tumor invasion and metastasis." (PMID 24520284, 2014). "Conversely, low GM3 levels but high CD9 levels enhance tumor cell motility through activating c-Src." (PMID 24520284, 2014). "In fact, both CD9 and claudin-3 proteins are present in TEMM on tumor cells and have been strongly linked to cancer malignancy." (PMID 25356755, 2014). "By contrast, in specific cases, CD9 appears to enable tumor cells to grow and proliferate more vigorously." (PMID 24520284, 2014). "In contrast to the enhanced effects on invasiveness by CD9-depletion, gene-depletion of CD9 inhibited tumor growth." (PMID 24466195, 2014). "High levels of GM3 expression interacting with high levels of CD9 cooperatively reduces tumor cell motility by inhibiting c-Src activation." (PMID 24520284, 2014). "All of these results show that the down-regulation of CD9 plays an important role in the development of tumor." (PMID 24788635, 2014). "Restore expression of CD9 in small cell lung cancer cells can significantly inhibit the proliferation and migration of tumor cells." (PMID 24788635, 2014). "A number of previous studies have analyzed the effect of the tetraspanin, CD9, on the life of tumor cells in several types of cancer." (PMID 24520284, 2014). "In the present study, we demonstrated that inverse correlation between CD9 and CD26 play a role on CD9-mediated suppression of invasiveness of CD26-positive tumor cells." (PMID 24466195, 2014). "Both false positive cases had a tumor size of over 35 mm, suggesting a higher diagnostic reliability for [high-ITGA3/CD9 and high-ITGB4/JUP] status in early OSCC." (PMID 24006899, 2013). "Our new data now establish that depletion of the CD9/CD81 complex can have a significant impact on α3β1 integrin function in tumor cells." (PMID 23613949, 2013). "Anti-CD9 was used in combination with appropriate secondary and alternative primary antibodies for detection of specific tumour markers in clinical samples." (PMID 26082317, 2013).
tumor (continued). "We utilized an invasive and metastatic human carcinoma cell line to explore the contribution of tetraspanin CD9 to tumor cell invasion." (PMID 23840773, 2013). "This potential relationship between CD9 expression and the tumor cell phenotype is supported by studies that used inhibitory anti-CD9 antibodies to decrease tumor weight in two separate in vivo models." (PMID 23840773, 2013). "Although converse functions have also been reported in certain tumors, downregulation of CD9 correlates well with tumor progression or metastasis in bladder, breast, lung and colon cancers." (PMID 23128478, 2013). "The tetraspanin superfamily proteins (TM4SF) mainly CD9, CD63, CD82, CD151 and CD81 have been implicated in cell migration, proliferation and tumor cell metastasis." (PMID 23128478, 2013). "The second substrate of ZDHHC2 related to its putative tumor/metastasis suppressor is tetraspanins CD9 and CD151." (PMID 23457560, 2013). "For example, in clinical studies, reduced expression levels of the tetraspanin CD9 are correlated with tumour progression in a range of cancers." (PMID 24351670, 2013). "The first major finding of our study is that the CD9/CD81 complex is in fact required for certain aspects of α3β1 integrin function in tumor cells." (PMID 23613949, 2013). "Primary site recurrence (PSR) was significantly associated with high-ITGA3/CD9, tumor size, T3-4 and positive margin, while distant metastasis was associated with high-ITGA3/CD9, a high ITGB4/JUP ratio (high-ITGB4/JUP), and YK4." (PMID 24006899, 2013). "Consistent with this, the tetraspanins, CD82 and CD9, possessing tumour supressor properties, down-regulate Wnt signaling through the exosomal discharge of β-catenin." (PMID 23173708, 2012). "Among others, perlecan, CD9 and fibronectin receptors were identified as promising circulating tumor marker." (PMID 22458520, 2012). "Recent studies showed that the CD9 expression level was closely related to tumor progression, metastasis and invasion of tumors and that tumors with low CD9 expression were strongly prone to metastasis and invasion." (PMID 22613496, 2012). "Immunoblotting with the anti-CD9 antibody of tumour lysates at the end of the treatments showed that tumours of vehicle-treated animals contained an important quantity of CD9." (PMID 21206492, 2011). "Analysis of CD9 showed that tumours from animals treated with GS-168AT2 for five successive days have less CD9 than those from animals treated with GS-168AT2 for 5 days." (PMID 21206492, 2011). "Although CD9 has been investigated in the progression and invasion of tumours, nothing or little has been shown about its main partner, an Ig superfamily member called partner 1 of CD9 (CD9P-1)/FPRP/EWI-F." (PMID 21206492, 2011). "The truncated form of CD9P-1, GS-168AT2, potently inhibits angiogenesis and cell migration by at least the downregulation of CD151 and CD9, which provides the first evidences for the central role of CD9P-1 in tumour-associated angiogenesis and tumour growth." (PMID 21863033, 2011). "The tetraspanins CD82 and CD9 mostly suppress tumour progression; their expression is often reduced in late-stage human tumours and their down-regulation during CRC progression is associated with poor prognosis." (PMID 21339979, 2010). "Expression of CD9 has been analysed in a number of tumours and seems, like syncytin expression, to correlate with a good prognosis." (PMID 22276010, 2009). "On the other hand, the present study indicates that reduced CD9 expression by tumour cells seems to predict disease progression after RT with or without chemotherapy." (PMID 14735195, 2004). "In a similar model, when substituting CD9 expression by tumour grading (G1 vs G2–3), the impact of the latter on DFS remained nonsignificant (P=0.3)." (PMID 14735195, 2004). "Most importantly, the serum levels of MCT1+ CD9+ EVs reflect the tumor burden in SS patients." (PMID 40679665, 2025).
tumor (continued). "As the composition of adhesion molecules (including tetraspanins) on EV membranes largely determines intercellular communication and contributes to an aggressive tumor phenotype, the presence of CD9-positive EVs could plausibly promote tumor progression." (PMID 40565320, 2025). "Initially, CD9 was primarily recognized as a tumor suppressor." (PMID 40860827, 2025). "Similarly, in HGSC, NK-cell cytotoxicity is dampened by the trogocytic acquisition of CD9 from tumor cells." (PMID 41181711, 2025). "As a cell surface protein, CD9 is involved in regulating cell-cell adhesion and interactions, which may affect the response of tumor cells to radiation therapy." (PMID 40530955, 2025). "This functional heterogeneity underscores the tissue-specific roles of CD9 in tumor biology." (PMID 40860827, 2025). "These contrasting findings highlight the complex role of CD9 in cancer progression and drug resistance, suggesting its effects may vary based on tumor stage, tissue context, or metastatic status." (PMID 39886381, 2025). "CD9, as an important member of the tetraspanin family, has gradually gained attention in cancer research in recent years and has become a hot research topic in the field of tumor biology." (PMID 40860827, 2025). "This trajectory suggests that CD9 may regulate tumor proliferation and migration by promoting the transition from NPC-like to OPC-like phenotypes." (PMID 40406701, 2025). "The researchers knocked out MMP3 in tumor organoids, highlighting MMP3’s dual role in tumoroid structure and EV integrity, showing that MMP3-rich EVs rescue proliferation and CD9/CD63 expression in deficient organoids, thereby positioning MMP3 as a key modulator of tumor EV function." (PMID 40806235, 2025). "Since EVs express tetraspanin family proteins such as CD63, CD81, and CD9, circulating EVs could be detected by these proteins as well as other tumor-specific markers." (PMID 40679665, 2025). "Interestingly, CD9 has a dual role in different types of tumors, acting both as a tumor suppressor and as a promoter of cancer during tumor development and metastasis." (PMID 40860827, 2025). "Furthermore, when we used super-resolution nanoimaging, we were able to confirm that the EBC of human lung tumor-bearing mice contained human tumor-derived EVs (positive for CD9, CD63, and CD81)." (PMID 38863869, 2024). "Additionally, NK cells in CN group underwent an increasing of tumor-infiltrated NK cells markers, CD9, CD49a, and PD-1, especially CD9." (PMID 39387546, 2024). "The enrichment of CD63/81+ and CD9/63/81+ sEVs in post-brachytherapy samples suggests that these subpopulations may be tumor-derived." (PMID 38892225, 2024). "In addition, CD9 also promotes drug resistance by mediating tumor microenvironments, such as the interaction between MSCs and tumor cells." (PMID 38389703, 2024). "It is possible that CD63/81+ and CD9/63/81+ sEVs may be tumor-derived, although further studies are needed to identify the origin of these vesicles." (PMID 38892225, 2024). "However, whilst the anti‐CD63‐APC or anti‐CD9‐PE fluorescence were well‐detectable in the fractions F16‐F17 in tumour samples (red, violet lines), it remained at the detection limit in the samples of healthy donors." (PMID 39441012, 2024). "This interaction results in increased tumor depth, size, LN metastasis and CD-9 expression." (PMID 37834127, 2023). "CD9, a member of the tetraspanin superfamily, is a tumor suppressor in many malignancies." (PMID 37241967, 2023). "In addition, a syngeneic C57BL/6 mouse tumor model with pancreatic cancer Pan02 showed an increased CD9-positive EV subpopulation in mouse plasma, which correlated with tumor growth." (PMID 37823055, 2023). "Besides studies dealing with the molecular function of CD9, expression of this gene was also monitored in large cancer patient cohorts concerning tumor aggressiveness and survival." (PMID 37007105, 2023).
tumor (continued). "CD9 has been proposed to have anti- and pro-tumor capability in different tumor lineages." (PMID 37542044, 2023). "CD9, a member of the tetraspanin superfamily, shows wide cellular and tissue distribution and is involved in cell motility, proliferation and metabolism in both immune cell and tumor cells." (PMID 37542044, 2023). "Notably, the significant increase in prevalence of CD147+ EVs was detected substantially earlier than for CD9+ EVs, that is at day 28 for CD147+ EVs when mean tumour size is 176 mm3 versus day 42 for CD9+ EVs when mean tumour size is 691 mm3." (PMID 36973758, 2023). "CD9 is also an exosomal marker and may affect the cellular exosomal transport and interactions between tumor cells and the stromal microenvironment (see chapter below)." (PMID 37007105, 2023). "In addition, the results of western blot revealed the expression of exosome specific marker proteins CD63, CD9, TSG101 (tumor susceptibility gene) in the supernatant of MDA-MB-231 cells, which further confirmed the presence of exosomes in BC cell supernatant." (PMID 37056561, 2023). "In addition, CD9 functioning as a marker of PDAC tumor-initiating cells promotes plasma membrane localization of glutamine transporter ASCT2 to enhance glutamine uptake, contributing to organoid formation capability and tumor grafts in vivo." (PMID 37845207, 2023). "According to in vitro and in vivo studies, tetraspanin CD9 is not clearly associated with either tumor suppression or promotion." (PMID 37007105, 2023). "The specific marker CD9 of dNK cells was also detected in tumour-infiltrating NK cells, which indicated that tumour infiltrating NK cells may be polarized into a decidual-like phenotype and thus reduce toxicity and promote tumour." (PMID 37386055, 2023). "The results for CD9 are contradictory because CD9 is generally a suppressor of tumor invasion and metastasis; however, in specific situations, CD9 may play a role in promoting invasion." (PMID 37587203, 2023). "CD9 may also play a critical role in controlling the HGSC (Tubo-ovarian high-grade serous carcinoma) tumor microenvironment." (PMID 37974170, 2023). "As described in the previous chapter, CD9 is not clearly associated with either tumor suppression or promotion." (PMID 37007105, 2023). "According to this network, we found that the exosome markers CD81, CD9, CD63, and TSG101 were associated with ANXA9, suggesting that ANXA9 may exist in exosomes in tumor tissues." (PMID 37294149, 2023). "Perhaps more importantly, inhibition of CD9 in xenograft models with low doses of JQ1 that did not demonstrated toxicity in the murine models was associated with marked tumor control." (PMID 37542044, 2023). "However, most of these findings have been obtained using tumor cell lines, whereas little is known about CD9 prognostic value." (PMID 35563166, 2022). "CD9 is ubiquitously expressed on various cells such as monocytes, macrophages, eosinophils, basophils, endothelial cells, epithelial cells, smooth muscle cells, and tumor cell lines." (PMID 35563422, 2022). "Intercepting EV-mediated intercellular communication in the tumor niche with an anti-CD9 Fab antibody, combined with direct targeting of cancer cells, could lead to the development of new anti-cancer therapeutic strategies." (PMID 36010551, 2022). "CD9 has been verified as a marker of PC stem cells and promotes tumour growth." (PMID 36282889, 2022). "Intercepting EV-mediated intercellular communication in the tumor niches (i.e., primary and secondary sites) with an anti-CD9 Fab, combined with direct targeting of cancer cells, could lead to the development of new anti-cancer therapeutic strategies." (PMID 36010551, 2022). "Generally, immuno‐based microfluidic and microarray technologies have utilised tetraspanins (CD9, CD81 and CD63) and tumour‐cell surface associated markers such as EpCAM, CA125, CD19, EGFR, EGFRvIII, podoplanin and PDGFR for on‐chip capture of tumour‐EV sub‐populations." (PMID 36239734, 2022).